CD4 (CD4 molecule)
Diseases named in the same sentence as CD4 in open-access papers (continued):
Sharing a sentence is not in itself a finding about the gene and the disease.
infection (continued). "Although the majority of infected cells in CD4-depleted animals were macrophages, it is possible that infection of these cells was a result of high viral loads, and they did not contribute substantially to the total viral load because they produced little virus per infected cell." (PMID 25356757, 2014). "In a previous work we found that the lower CD4+T cell levels observed in class IA, IB and II M4 haplotype animals in the chronic phase of infection were concomitant with the lower proviral DNA values associated with class IB and II M4 haplotype in acute infection." (PMID 24695530, 2014). "Infection of CD4 T cells was detected approximately 70% of the time." (PMID 25299616, 2014). "It is unclear whether such an effect is direct, or secondary to microbial translocation due to gut CD4+ T cell depletion seen early in infection." (PMID 24586620, 2014). "Following Lm-2W infection, three subsets of 2W1S-specific CD4+ T cells have been elegantly described 19: CXCR5−PD-1−T-bet+ effector T cells (where PD-1 is programmed death-1), CXCR5+PD-1−Bcl-6+ cells that give rise to central memory cells and CXCR5+PD-1+Bcl-6+ TFH cells." (PMID 24771127, 2014). "A3D, F, G, and H but not A3B, C, and DE restrict infection of human CD4+ T lymphocytes by Vif-deficient viruses." (PMID 25352838, 2014). "Finally, we show that inhibiting differentiation of naïve CD4 T cells to TFH cells in wild type mice results in impaired establishment of MHV68 infection." (PMID 24789087, 2014). "More importantly, the antigen induced a significantly higher proportion of multipotent CD4+ T cells that simultaneously express all the three Th-1 cytokines and resulted in a significantly increased protection of mice from L. major challenge infection." (PMID 25500571, 2014). "Indeed, low expression of CD4 or CCR5 can completely inhibit infection of CD4+ T cells by certain viral strains." (PMID 24811311, 2014). "However, in this scenario, the ongoing CD4+ T-cell response would also produce IL-13 and data from the N. brasiliensis system suggest that the CD4+ T cell is critical to control of secondary infections." (PMID 24942690, 2014). "Furthermore, we discovered a link between MT levels and infection parameters in experimentally infected Chinese macaques, including plasma viral load, CD4+ T cell count, presence of infectious virus, and route of infection." (PMID 25759828, 2014). "Moreover, infected mice treated with the anti-malarial drug chloroquine at day 8 and 9 post-infection, showed a lower level of CD4+ T cell dysfunction." (PMID 24904561, 2014). "This was further confirmed in a study by King and Mohrs that demonstrated that in a Th2 setting induced by infection with H. polygyrus, the majority of IL-4 producing CD4+ T cells in the reactive lymph nodes co-express canonical TFH cells markers and localised within the B cell follicles." (PMID 24516382, 2014). "This eicosanoid that is released during infection may promote the activation of dendritic cells, which influence the release of mediators involved in the drive of naive CD4+ T lymphocytes to the Th17 profile." (PMID 25309905, 2014). "The dynamics of CD4+ and CD8+ T-cells are altered in many ways during HIV infection, with both showing evidence of early increased proliferation and subsequent preferential loss of the naive subset as untreated infection progresses." (PMID 24816636, 2014). "In separate experiments, we observed that developmental AhR activation caused the same alterations in CD4+ T-cell responsiveness to infection in all three congenic strains of mice (data not shown)." (PMID 25051576, 2014). "Although CD4+T cell and CD8+T cells also have a protective effect during the pathogen infection, especially during high pathogenic avian influenza viruses infection, the protective was also seen in the absence of all T and B cells as well as in the depletion of neutrophils or NK cells." (PMID 24666970, 2014).
infection (continued). "Indeed, at later stage of infection IL–21 was present in the lung mostly derived from IAV-specific CD4+ T cells entering the infected lungs from the dLN." (PMID 25251568, 2014). "Furthermore, by demonstrating the susceptibility of TSCM to infection by C-HIV, our results highlight the potential for this subset of CD4+ T-cells to serve as a long-lived viral reservoir in individuals harboring CCR5- and CXCR4-using C-HIV viruses." (PMID 25387392, 2014). "Nevertheless the increasing likelihood of ×4 and dual-tropic virus with lower CD4+T cell count may add support for delivery of this combination gene therapeutic to early stages of infection." (PMID 24945407, 2014). "In addition, high dose infection was associated with strong upregulation of MHC class II molecules on DCs, which would potentially favor activation CD4+ T cells." (PMID 25412267, 2014). "Collectively, these observations suggest that the role of CD8+ T cells may be limited to helping for optimal activation of CD4+ Th1 cells during primary infection." (PMID 25412267, 2014). "It is currently unknown whether particular cytokines produced during infection are required for the differentiation and maintenance of memory CD4+ T cells." (PMID 24842874, 2014). "Depletion of CD4 T cells is believed to be mostly due to direct infection of this subset." (PMID 25610441, 2014). "Then, using reciprocal adoptive transfers, we evaluated whether CD4+ T-cell responses to infection were modulated via intrinsic or extrinsic effects of AhR activation during development on CD4+ T cells in adult mice." (PMID 25051576, 2014). "On the contrary, CD4+CD25− T cells showed lower expression of Foxp3 mRNA during infection." (PMID 24926293, 2014). "Latency could also result from infection of resting CD4 T cells or de-activation of activated CD4 T cells." (PMID 25340797, 2014). "We utilized the same amounts of VSV-G pseudotyped NLENY1-ES-IRES (WT for short) and NLENY1-ΔVpr (ΔVpr for short) viruses to infect the CD4+ T cells called Jurkat and harvested the infected cells 2 hours after infection before viral proteins were newly synthesized." (PMID 24912525, 2014). "For patients with HCV mono-infection, the CD4+ and CD8+ cell counts were normal." (PMID 24693316, 2014). "Lower antibody responses may have resulted into a poor control of infection thus explaining the previously reported lower CD4 T cell counts in these monkeys." (PMID 24695530, 2014). "CXCR4-tropic (X4) HIV-1 was found to kill resting spleen and tonsil CD4+ T cells ex vivo through abortive infection, whereas double-stranded DNA breaks occurring during HIV-1 integration were responsible for the death of productively-infected CD4+ T cells from peripheral blood." (PMID 24495380, 2014). "In the present study, we examined whether AhR activation during development changes the response of CD4+ T cells to infection with IAV later in life." (PMID 25051576, 2014). "Coevolution of virus and host may have selected for limited MTIT by decreased expression of CCR5 on all CD4+ T cell subsets in infants with widespread infection of older animals due to moderate expression of CCR5 on effector memory T cells." (PMID 24604066, 2014). "Why would high and low dose infections differentially activate CD4+ and CD8+ T cells, respectively?" (PMID 25412267, 2014). "However, our analysis of infected lungs did reveal significantly elevated numbers of T cells on day 3 post-infection, with both CD4 and CD8 showing an activated CD44hi phenotype." (PMID 24809749, 2014). "If infection of a rare superspreader CD4+ T cell establishes the founder strain, then the few features of founder viral strains that have been observed might in fact confer a selective advantage during early infection." (PMID 24811311, 2014). "Both CD8+/CD69+ and CD4+/CD69+ T cells were significantly elevated early in infection." (PMID 24658451, 2014).
infection (continued). "To address this issue, we studied a group of stringently defined VNPs and, in contrast to previous studies, we compared them to HIV-infected individuals with similar CD4+ T-cell counts and viral load, mainly in early infection (i.e. “putative progressors”; PP)." (PMID 25167059, 2014). "In a single round of infection, virus collected from infected, Velcade-treated primary CD4+ T cells [PI (virus)] was only able to infect approximately one fourth the number of HeLaT4 cells as virus collected from infected, untreated primary CD4+ T cells." (PMID 24156270, 2013). "In fact, an older age at primary infection implies a lower value of the age-dependent CD4+ T cells recruitment parameters, and therefore a delayed availability of effector CD4+ T cells, thus increasing the chances of active TB, as previously found in aged mice." (PMID 23580062, 2013). "Vaccine-specific CD4+ T cells producing IL-2 are a desirable outcome of vaccination as these cells are now understood to be preserved in response to infection and to participate in suppression of viremia levels post infection." (PMID 23977084, 2013). "Interestingly, TNF-α/IL-2 expressing central memory-like CD4 T cells showed a significant positive correlation with protection at week 6 post infection, whereas the opposite was observed for post infection CD4 T cells producing only IFN-γ." (PMID 23977248, 2013). "Thus, BAD-1 mimics TSP-1 and is capable of suppressing activation and effector functions of T cells, in this case CD4+ T cells that confer resistance to infection." (PMID 23853587, 2013). "Interestingly, normalization of mDC activation occurred before complete control of SIVagmSab infection in RMs, in contrast to CD4+ T cell activation that normalizes long after the control of viral replication." (PMID 24098110, 2013). "However, later evidence supported that entry via CD4/CCR5 receptors on LC leads to trans infection of CD4+ T cells." (PMID 24278768, 2013). "CD4+ T cells rapidly die by apoptosis upon acute infection showing a half-life of a few days." (PMID 24009706, 2013). "Thus, different mechanisms seem to mediate protection depending on the mouse model, the T. cruzi strains used for infection and the CD4+ T cell subset studied." (PMID 23776551, 2013). "We then used these cells as donors to transfer the infection to autologous activated CD4+ T cells." (PMID 23899341, 2013). "The CD4+-enriched cell line was much more efficient at clearing infection." (PMID 23457650, 2013). "Thus such treatment does not promote reconstitution or regeneration of proliferative HIV-1-specific CD4 T-cell responses with the potential to control viremia and protect CD4+ cells from infection and destruction – facilitating discontinuation of cART." (PMID 23459797, 2013). "We found that Rag1−/− mice and RAG+CD8 mice had similar numbers of parasites at the infection site, in spite of the disparity in lesion size observed in these animals, while transfer of CD4+ and CD8+ T cells into Rag1−/− mice led to significantly better control of the parasite in the infected ear." (PMID 23874205, 2013). "This would arise from the presence of multiple virions potentially present at the site of transfer that may enter the target cell before mechanisms to suppress multiple infection, such as downregulation of CD4, can take place." (PMID 23772628, 2013). "These contradictions were later resolved when it was shown that following low dose infection CD8+ T cell produced IFN-γ was necessary for the development of Th1-polarized CD4+ T cells, while after high dose infection CD8+ T cells were not required for the generation of a protective Th1 response." (PMID 24741372, 2013). "Importantly and in contrast to CD4+ T cell populations, which recognise antigens solely expressed during lytic infection, include a subset of cells that secrete the immunosuppressive cytokine cIL-10." (PMID 24130479, 2013).
infection (continued). "Based on the finding that CD4+ and CD8+ T cells produced IL-10 after Clone 13 infection and that CD4+ T cell depletion decreased IL-10 mRNA levels on day 5 post infection, we investigated if T cell derived IL-10 complements macrophage derived IL-10 to exert it's biological effects." (PMID 24244162, 2013). "In contrast to the preservation of peripheral CD4 T cells in macaques infected with SIVmac239Δnef, we found that peripheral CD4 T cell levels declined during the acute phase of infection in all of the animals, independently of the MHC genotype, and then rebounded." (PMID 23785211, 2013). "We performed a comparative study of the dynamics of CD4+ T cell subsets after infection with the T. cruzi Y strain during both the acute and chronic phases of the disease using susceptible BALB/c and non-susceptible C57BL/6 mice infected with high or low parasite inocula." (PMID 23776551, 2013). "Given that HIV-1 preferentially infects activated CD4 T-cells, coupled with the ongoing generation of memory cells, the consensus is that infection prior to or during deactivation is the major route of establishment of latency, although this remains an unresolved issue." (PMID 23375003, 2013). "Moreover, we compared LC3 staining in uninfected bystander cells (Gag−) and HIV-1 infected CD4+ T cells (Gag+, green) found within infected samples five days after infection and found that the formation of LC3 puncta was mostly confined to Gag+ target cells." (PMID 23658518, 2013). "However, it has been demonstrated previously that HIV is present in both central and effector memory CD4 subsets 17, and the mechanism of infection of these different subsets and establishment of the latent HIV reservoir in each is still poorly understood." (PMID 23772628, 2013). "Supporting evidence that HIV-1 cis and trans infection mediated by MDDC is a significant gauge of HIV-1 pathogenesis is that differentiation of monocytes into CD1a+ DC in vitro correlates with low CD4+ T cell counts and high viral loads in HIV-1 infected adults." (PMID 24278768, 2013). "Thus, the higher cortical actin density of memory CD4+ T cells was associated to increased efficiency of HIV-antigen internalization and the establishment of a productive infection." (PMID 24244453, 2013). "CMV-Specific (Sp)-CD8 and CD4 T cells are crucial in the control of CMV-infection." (PMID 24130889, 2013). "Following infection with N. caninum in cattle, CD4+ T lymphocytes are principal components of the Th1 response and produce pro-inflammatory Th1 type cytokines including IFN-γ, TNF-α and IL-12, which have an essential role in protective immunity against the parasite." (PMID 23876124, 2013). "The observation that such effector cells, especially large populations of proliferative Gag-specific CD4 T-cells, are not often seen in subjects who had progressive infection and have suppressive cART argues in favor of a causal relationship." (PMID 23630526, 2013). "This could therefore suggest a recent infection with the characteristic low viral load high CD4 cell counts profile." (PMID 23759122, 2013). "This immunosuppressive microenvironment may also have an impact on the generation of CD4+ T cells activated during latent phases of infection." (PMID 24130479, 2013). "Defense against infection by Mycobacterium tuberculosis (Mtb) is mediated by CD4 T cells." (PMID 24220507, 2013). "This feature can most likely promote HIV-1 capture, and may partly explain the noticed cis-infection of CD4+ T cells with X4 virus." (PMID 23844079, 2013). "Highly productive HIV-1 trans infection requires activated CD4+ T cells." (PMID 24278768, 2013). "However, SGE-1X treatment enhanced the number of CD4+FOXP3+ cells by three- to four-fold in the site of infection." (PMID 23656976, 2013).
infection (continued). "The cytokine storm associated with symptomatic PHI certainly plays a role in this rapid systemic dissemination throughout the immune system, and a viral setpoint is established between 21 to 28 days post-infection, while homeostatic cytokines compensate for this global CD4 cell depletion." (PMID 23691172, 2013). "Further, these patients developed a subsequent infection at least 6 days following blood sampling; therefore, this may have been due to a dysfunction in the adaptive immune response, such as with CD4+ T cells." (PMID 24289156, 2013). "Latency may be established when infected CD4+ T lymphoblasts revert back to a resting state that is non-permissive for viral gene expression or through direct infection of resting CD4+ T cells." (PMID 23816179, 2013). "Infection-induced syncytia in NP-2/CD4/CCR6 cells were detected by Giemsa staining." (PMID 24009735, 2013). "Our IF experiments showed that DCs and CD4+ T cells were closely colocalized on day 7 of infection, which might indicate a modulation of DC activation by some CD4+ T cell types, such as Tregs." (PMID 24312297, 2013). "According to the data of subject 1175 we previously reported, HIV-1 DNA in monocytes and CD4+ T cells had homogenous sequences in the env C2-V5 regions during acute infection stages, however significant compartmentalization and variation were found in late stages." (PMID 23741458, 2013). "In fact, we found high numbers of CD4+Foxp3+GFP+ Tregs within the liver on day 7 of infection, which corroborates this hypothesis." (PMID 24312297, 2013). "However, other work has argued that similar levels of infection and depletion of CD4+ T cells are seen in the upper gastrointestinal tract and rectal biopsy." (PMID 24119218, 2013). "Since IL-10 secretion by CD4+ CD25+ FoxP3+ Treg cells as well as CD4+ CD25− FoxP3− Th1 cells has been implicated in the control of chronic infection with Leishmania, it was important to determine the T cell population secreting IL-10 early after infection." (PMID 23825956, 2013). "However, at day 21 post infection CD4+ Teff cell numbers were significantly reduced over controls in RRV-infected NOD mice (p = 0.022), whereas Treg numbers were unaltered (p = 0.079)." (PMID 23554993, 2013). "However, another study using the respiratory route of infection demonstrated that intranasal infection with Chlamydia requires B cells for efficient CD4 T cell activation." (PMID 24204262, 2013). "However, one must note that nearly all of the CD4+ T cells expressed BTLA in the majority of septic patients who developed a secondary infection." (PMID 24289156, 2013). "Latently HIV-1-infected resting CD4+ T cells are apparently established early in infection." (PMID 24086129, 2013). "In addition, when both ICAM-1 and LFA-1 were simultaneously blocked, inhibition of mDC-mediated trans-infection of HIV-1 to primary CD4+ T cells reached 75% to 90% in both autologous and allogeneic co-cultures (p < 0.05)." (PMID 23590845, 2013). "First, the frequency of proliferating PD-1+CD8+ T cells peak during the acute phase of infection followed by a decline at the initiation of the chronic phase paralleling plasma viral loads, while PD-1+CD4+ T cells gradually increase during the course of infection." (PMID 23555918, 2013). "The association of early mortality rate with CD4 count at initiation of HAART is lost for diagnosis delays equal to or higher than 8 years since according to our prediction after that time of infection patients are diagnosed harboring a median CD4 count of 200 cells/μl." (PMID 23308161, 2013). "However, direct infection of resting T-cells is very inefficient, with defects in reverse transcription and delays in integration in comparison with infection of activated CD4+ T-cells." (PMID 23364195, 2013). "Therefore, protection against infection seems to be dependent not only on the magnitude but also on the quality of the CD4+ T cell response generated." (PMID 23840706, 2013).